SOX6 (SRY-box transcription factor 6)
Diseases named in the same sentence as SOX6 in open-access papers (continued):
Sharing a sentence is not in itself a finding about the gene and the disease.
tumor (continued). "To further explore the downstream mechanisms of SOX6 in tumor metastasis, we performed transcriptome sequencing to compare gene expression profiles between i) SOX6-overexpressing (OE) vs. empty vector (Mock) A375 cells; and ii) wild-type (WT) vs. SOX6-knockout (KO) A375 cells." (PMID 40866912, 2025). "Moreover, through RNA sequencing analysis in tumor CD8+ T cells, we found that genes associated with effector functions, such as Sox6, Ccnd1, CD81 and Trim14, were upregulated, while genes associated with immune inhibition, such as Tox, Jun-b, Btla, Batf and Foxp1 were downregulated 25-27." (PMID 38994031, 2024). "Animal experiments will be required to confirm whether SOX6 acts as a tumor suppressor." (PMID 31729835, 2020). "Thus, our results suggest that SOX6 may also have oncogenic properties, and that its oncogenic or tumor-suppressive function may depend on the cellular context." (PMID 32415069, 2020). "Interestingly, the effects of recombinant CCN2 peptide on U-CH1 cells were more pronounced under normoxia than hypoxia, promoting increased expression of CCN1, CCN2, CCN3 and CCN5, the notochord-associated markers SOX5, SOX6, T, CD24, and FOXA1 as well as increased tumour-sphere formation." (PMID 25541962, 2014). "To elucidate the role of SOX6 in PACAP38-mediated tumor suppression, we employed siRNA-mediated knockdown and lentiviral overexpression of SOX6 in tumor cell lines in T47D and T98G cells." (PMID 39619607, 2024). "To further verify the mechanism on the SOX6‐induced senescence of CC cells, we detected the effects of SOX6 in the MAP4K4/WT1–ATF2–TGFβ2 pathways in above xenograft tumor tissues." (PMID 38383842, 2024). "Together, these data confirm the ability of SOX6 to repress LIN28B and the pro-proliferative genes downstream to the LIN28/Let-7 axis, pointing to a wide tumor suppressor role of SOX6." (PMID 38704454, 2024). "We observed statistically significant differences in the expression of SOX6, SOX8, SOX21 and SOX30 genes in healthy tissue vs. primary tumor samples." (PMID 38132438, 2023). "Our results clearly point to SOX6, SOX8 and SRY as factors which are characteristic for a tumor tissue." (PMID 38132438, 2023). "SOX6, a member of the SOX family, is known to act as a tumor suppressor in many cancers and participates in the regulation of various malignant behaviors, such as cell proliferation and drug resistance and induction of apoptosis." (PMID 38062424, 2023). "Surprisingly, multiple previously reported tumor suppressors of KIRC were found in these downregulated genes, including SOX6, DAPK1, PDZK1, TXNIP, DAB2IP, and CMTM4." (PMID 37737260, 2023). "The majority of the tumor cells were in the intermediate state, which was governed by the EGR3, NFATC2, and SOX6." (PMID 35903095, 2022). "In conclusion, we showed that Sox6 plays a tumour suppressor role in PC, inhibiting EMT and tumour metastasis by modulating Twist1 expression through the recruitment of HDAC1 to the promoter of the Twist1 gene." (PMID 29369542, 2018). "PC elevation combined with LPC decrease may promote tumor invasion by activating ECM-receptor interactions and HIPPO-YAP signaling pathway, which were detected in enriched KEGG pathway of ST_high and SOX6_OE UPPER genes." (PMID 40866912, 2025). "We cannot exclude that additional molecular mechanisms/pathways downstream to SOX6, independent from LIN28B downregulation concur to the observed tumor suppressive outcome and it is also likely that reduction of LIN28B expression does not exclusively impact the Let-7 axis." (PMID 38704454, 2024). "In summary, we have revealed a tumor-promoting role of FBXO2 and a connection with SOX6 in OV." (PMID 35525855, 2022). "Finally, we found that the SOX6 and SOX12 expression levels were correlated with tumor-infiltrating immune cells (TIICs)." (PMID 34868396, 2021). "Our data revealed that SOX6 and SOX12 might play a specific role in the immunosuppressive tumor microenvironment by regulating regulatory T cells (Tregs)." (PMID 34868396, 2021).
tumor (continued). "With the exception of clonal Pdgfra and Nav3 insertions in one tumor, transposon insertions in MAPK/PI3K pathway and neurodevelopmental genes (including Nf1, Pten, Pik3r1, Ptprj, Sox6, Sox5, and Tcf4) were subclonal in these tumors, implying these were late evolutionary events." (PMID 32727536, 2020). "Unlike the oncogenic roles of these Sox family members, Sox6 has been reported to play a tumour suppressive role in different cancers." (PMID 29369542, 2018). "Since PTEN, WNK2, SOX6, BTG3, and RBSP3 have putative miR-18a-binding sites in their 3′-UTRs and act as tumor suppressors in CC, we hypothesized that miR-18a enhances PD-L1 expression via targeting these candidate targets." (PMID 29855617, 2018). "SOX6 suppressed ESCC cells proliferation and cell motility, and inhibited tumor formation." (PMID 25023649, 2014). "Furthermore, the observed interactions between immune and tumour cells, including those involving transcription factors such as MYB and SOX6, emphasise the interplay between transcriptional regulation and cell communication in shaping the immune landscape of HB." (PMID 40099956, 2025). "The results revealed that SOX6 could also induce cisplatin resistance of xenograft tumor, but the combined treatment with ABT‐263 could significantly reduce the volumes, sizes, and weights of the cisplatin‐resistant xenograft tumor in mice." (PMID 38383842, 2024). "Moreover, SOX6 and SOX10 had a low expression in HCC, which also indicated high grade of tumor." (PMID 35465267, 2022). "There existed a negative relationship between the expression of SOX6 and tumor stage (P < .05)." (PMID 36595751, 2022). "Notably, SOX6 protein expression was significantly positively correlated with the speed of tumor growth and Ki67 immunoreactivity in EwS patient-derived xenograft (PDX) models, in which we observed a broad range of SOX6 expression levels similar to that in primary EwS tumors." (PMID 32415069, 2020). "Furthermore, the presence of such connections in other cellular systems and the known involvement of SOX6 (a paralog of SOX2) in Wnt signaling, strengthens the importance of these findings within the broader context of cell regulation and signaling pathways in the tumor microenvironment." (PMID 38003292, 2023).
cancer (39 papers, 2012 to 2026). A tumor composed of atypical neoplastic, often pleomorphic cells that invade other tissues. "Though SOX6 has emerged as a promising therapeutic target across multiple cancer types, the precise mechanisms underlying its deregulation and subsequent alteration of downstream cellular events remain incompletely understood." (PMID 40866912, 2025). "The rs3746444 polymorphism present in the miR-499 would target to SOX6 and Rod1 genes important roles for the etiology of cancers." (PMID 23155448, 2012). "This context-dependent duality underscores the critical importance of considering tissue-specific regulatory mechanisms when evaluating the multifaceted roles of SOX6 in cancer biology." (PMID 40866912, 2025). "The same phenomenon was also found for ABT‐199 treatment but was weak in those cells without Dox treatment, suggesting that the two senolytics selectively eliminated the SOX6‐induced senescent cancer cells." (PMID 38383842, 2024). "PACAP38 synergizes with irradiation to suppress the proliferation of multiple cancer cells via regulating SOX6/Wnt/β-catenin signaling." (PMID 39619607, 2024). "In liver cancer, miR-1269a rs73239138 can prevent miR-1269a from binding to the 3′-UTR of SOX6, thereby inhibiting the development of cancer." (PMID 35252180, 2022). "The presence of this mismatch will affect Sox6 and Rod1 genes, which are important for the occurrence of cancers." (PMID 33816633, 2021). "Apart from its role in regulating growth and development, our and other groups have found that SOX6 can also regulate the proliferation of cancer cells." (PMID 34930918, 2021). "Some studies have shown that the abnormal expression of Sox6 is related to the occurrence and development of cancer." (PMID 31729835, 2020). "In non-small cell lung cancer, miR-1269a was upregulated and it acted as an onco-miRNA in NSCLC and promotes cancer cell growth through downregulating the expression of SOX6." (PMID 32709240, 2020). "Data from the Human Protein Atlas database showed that immunohistochemistry staining of SOX6 protein was higher in GBM cancer tissue compared with normal tissue." (PMID 32388501, 2020). "Comparative analyses revealed that SOX6 is overexpressed in EwS relative to normal tissues and other cancers." (PMID 32415069, 2020). "Recent data show that SOX6 expression is altered in different cancers, in the majority of cases being downregulated." (PMID 30833651, 2019). "The presence of this mismatch would affect Sox6 and Rod1 genes, which are important in the etiology of several cancers." (PMID 28978158, 2017). "The presence of this mismatch would affect Sox6 and Rod1 genes, which are important for the etiology of cancers." (PMID 24278149, 2013). "The upregulation of multiple lineage plasticity genes, including basal (Trp63, Krt5 and Krt14), metastasis (Snai2, Tgfb1 and L1cam), and stemness (Sox2, Mecom and Sox6) markers was induced by LKB1 loss, further supporting the enhanced cancer cell state plasticity by LKB1 loss." (PMID 39743630, 2025). "Several studies have previously investigated the roles of CCND1, GABPA, HIF1A, and SOX6 in various diseases, including cancer and cardiovascular diseases, but the specific roles of these genes in HF and their interaction within the context of the PI3K/AKT pathway have not been well-explored." (PMID 40818967, 2025). "Our research revealed that PACAP38 exerted its anti-cancer effects by upmodulating SOX6 expression." (PMID 39619607, 2024). "Currently, no studies have reported whether PACAP38 might influence the initiation and advancement of cancer by regulating SOX6." (PMID 39619607, 2024). "Thus, we performed western blot assays in T47D and BT-549 cells to elucidate the mechanism responsible for the anti-cancer effects mediated by the PACAP38/SOX6 axis." (PMID 39619607, 2024).
cancer (continued). "Colony formation assays indicated that knockdown of SOX6 could reverse the suppression of PACAP38 on T47D and T98G cells proliferation, which indicated that the capacity of PACAP38 to suppress cancer cells proliferation is dependent upon upregulating SOX6." (PMID 39619607, 2024). "Based on this research, we reason that PACAP38 may suppress cancer proliferation via upregulating SOX6 expression." (PMID 39619607, 2024). "However, when PACAP38 was applied concurrently with the knockdown of the SOX6 gene in cancer cells, the inhibitory effects of PACAP38 on proteins associated with the Wnt/β-catenin pathway were reversed." (PMID 39619607, 2024). "Since senolytics could selectively eliminate the senescent cancer cells, we further explored whether senolytics treatment could overcome the SOX6‐mediated cisplatin resistance." (PMID 38383842, 2024). "Oppositely, SOX6 overexpression inhibits the proliferation of cancer cells and promotes apoptosis." (PMID 38132438, 2023). "Data collected in recent years suggest that SOX6 expression is deregulated in different cancers." (PMID 30833651, 2019). "In addition, several studies have found that miRNA promoted the proliferation, migration and invasion of cancer cells and inhibited apoptosis by targeting SOX6." (PMID 31076992, 2019). "Indeed, SOX6 has been described as a tumor suppressor gene in various cancers." (PMID 34440750, 2021). "Additionally, SOX6 may serve as a biomarker to predict the efficacy of Elesclomol-treatment in EwS, and perhaps other cancer types." (PMID 32415069, 2020). "miR-1269a can regulate the occurrence and development of cancer by targeting downstream genes (CXCL9, SOX6, FOXO1, ATRX, RASSF9, SMAD7, HOXD10, and VASH1)." (PMID 35252180, 2022). "Collectively, these data suggest an essential role of SOX6 in regulating cell survival and death mechanisms in GBM cancer." (PMID 32388501, 2020). "PTEN, SOX6, WNK2, BTG3, and RBSP3 protein expression was decreased in miR-18a-overexpressing CC cells but was increased in miR-18a-silenced cancer cells." (PMID 29855617, 2018). "For example, SOX5 and SOX6, members of the SOXD family, were frequently underexpressed concurrently in several cancer types." (PMID 25594027, 2014). "ABT‐263 could significantly increase the levels of apoptosis‐related proteins in the SOX6‐mediated cisplatin‐resistant HeLa‐HA‐SOX6‐tet cells, suggesting that ABT‐263 could promote apoptosis of the SOX6‐induced senescent cancer cells." (PMID 38383842, 2024). "Furthermore, our study screened a set of cancer cell genes in different stemness-related signaling pathways, including CTNNB1, SOX6, and CD133 in CCA, to show that stemness genes were targeted by m6A modification." (PMID 34347395, 2021). "SOX6 directly activates transcription of aggrecan (Acan) and expression of MMP12 in cancer tissue." (PMID 34440750, 2021). "Our results show that SOX6 is a direct EWSR1-FLI1 target gene that is highly but variably overexpressed at the mRNA and protein level in EwS as compared to most normal tissues and other cancers." (PMID 32415069, 2020). "In addition, the level of SOX6 protein significantly decreased under ABT‐263 treatment, indicating that ABT‐263 could efficiently eliminate the SOX6‐induced senescent cancer cells." (PMID 38383842, 2024). "Mechanistically, Lin28B repression is accompanied by SOX6 physical binding within its locus, suggesting a direct mechanism of LIN28B downregulation that might contribute to the fetal/adult erythropoietic transition and restrict cancer proliferation." (PMID 38704454, 2024).
myopathy (3 papers, 2013 to 2022). A disease of the muscle in which the muscle fibers do not function properly. "The mouse with p100H / p100H mutant, a Sox6 null mutant, is characterized by early postnatal lethality, associated with progressive atrioventricular heart block and myopathy." (PMID 24040263, 2013). "Murine SOX6 null mutants (p100H) show delayed growth, myopathy, and atrioventricular heart block and die within 2 weeks following birth." (PMID 29333458, 2017). "Sox6 gene disruption in mouse resulted in growth retardation, myopathy." (PMID 36232654, 2022).
infection (2 papers, 2013 to 2022). The state of being infected such as from the introduction of a foreign agent such as serum, vaccine, antigenic substance or organism. "Retrovirus-mediated overexpression of Sox6 in NSPCs increased cell viability by 2.1±0.12 fold 5 days after infection, whereas retrovirus-mediated silencing of Sox6 decreased cell viability by half (0.50±0.02 fold) 4 days after infection." (PMID 24066135, 2013). "In addition, a small group of transcription factors was predicted to be inhibited only upon infection with amastigotes (SOX6, RUNX3, and STAT1) or promastigotes (TRIM24, SIRT1, and FOXP3)." (PMID 35430587, 2022).
skeletal dysplasia (2 papers, 2009 to 2022). Any Mendelian diseases that affects growth and development of the skeleton. "Although mice deficient in Sox5 or Sox6 alone survive with mild skeletal dysplasia, the formation of cartilage in Sox5/Sox6 double-knockout mice is harshly compromised." (PMID 36339269, 2022). "Mouse SOX5/SOX6 double knockouts die in utero with severe skeletal dysplasia, demonstrating that these two genes have critical, redundant roles during development." (PMID 19521496, 2009).
heart disease (1 paper, 2016). "Downregulation of H19 promoted cell proliferation and inhibited cell apoptosis during late-stage cardiac differentiation by regulating the negative role of miR-19b in Sox6 expression, which suggested that the manipulation of H19 expression could serve as a potential strategy for heart disease." (PMID 27895893, 2016).
SOX6 also shares sentences with these, for which no sentence is quoted: esophageal squamous cell carcinoma (7 papers); prostate carcinoma (4); cardiovascular diseases (2); fibrosis (2); Insulin resistance (2); multiple myeloma (2); acute myocardial infarction (1); Alzheimer disease (1); atrial fibrillation (1); autoimmune disease (1); bladder carcinoma (1); brain diseases (1); colitis (1); colorectal adenocarcinoma (1); fibromyalgia (1); Hyperinsulinemia (1); idiopathic scoliosis (1); inflammatory bowel disease (1); Kashin-Beck disease (1); left ventricular hypertrophy (1); liver diseases (1); migraine (1); movement disorder (1); muscular disease (1); myeloproliferative disorder (1); neurodevelopmental disorder (1); neurological diseases (1); oral submucous fibrosis (1); Parkinsonism (1); Pectus carinatum (1).
A further 8 diseases each share a sentence with SOX6 in 1 paper.